ENSG00000226149 (novel transcript)
Gene: Long non-coding RNA gene on chromosome 6 (129,439,485 to 129,576,047, reverse strand). Ensembl gene ENSG00000226149.
Gene Ontology:
Molecular function: structural constituent of ribosome
Cellular component: ribosome